FOXM1 (forkhead box M1)
Diseases named in the same sentence as FOXM1 in open-access papers (continued):
Sharing a sentence is not in itself a finding about the gene and the disease.
tumor (continued). "In xenograft mouse model, the combination of radiation and FoxM1-shRNA led to a synergistic anti-tumor effect." (PMID 36860922, 2023). "FOXM1 is an important regulator of many biological processes, and dysregulation of FOXM1 leads to carcinogenesis and tumor progression." (PMID 36726012, 2023). "FOXM1 promotes tumor cell proliferation by activating genes involved in cell cycle progression and DNA synthesis." (PMID 37904848, 2023). "We observed that RNF112 noticeably decreased tumor growth and weight in vivo, coupled with the decreased FOXM1 and its downstream genes’ expression." (PMID 37288663, 2023). "In corroboration with the in vitro results, the in vivo study of murine xenograft model revealed that FoxM1 suppression by shRNA significantly impeded tumor growth, which was further enhanced when combined with radiotherapy." (PMID 36860922, 2023). "We analyzed the relationship between the FOXM1 expression and the prognosis, survival rate, tumor stage, and lymph node metastasis of HCC patients through TCGA data." (PMID 37234166, 2023). "FOXM1 activates the expression of target genes at the transcriptional level, and the dysregulation of its activity can be observed in all hallmarks of tumor cells." (PMID 37373974, 2023). "Treatment with FoxM1-shRNA or IR alone moderately reduced tumor burden and weight in mice bearing Eca-109 subcutaneous tumors compared with the NC group (FoxM1-shRNA: T/C%= 51.1%; NC+IR: T/C%=41.1%)." (PMID 36860922, 2023). "lncRNA-SH3PXD2A-AS1 interacted with DHX9 to enhance FOXM1 expression, promote tumor cell proliferation, and accelerate cell cycle progression; lncRNA-KIMAT1 binds to and stabilizes DHX9, this effect is attributable to proteasomal degradation." (PMID 37048101, 2023). "Stable DEPDC1 over-expression can facilitate cell proliferation and tumor growth via upregulating FOXM1 in MDA-MB-436 cells and BT549 cells." (PMID 36424525, 2023). "By identifying patients with high FOXM1 expression, clinicians can anticipate a potentially aggressive tumor behavior and adjust treatment regimens accordingly." (PMID 37817774, 2023). "Antitumor growth response, which was measured as change in mean tumor weight, indicated an additive effect of the combined FoxM1-shRNA and IR on tumor growth inhibition (vs. FoxM1-shRNA p= 0.002; vs. NC+IR p= 0.009)." (PMID 36860922, 2023). "MiR-26b functioned as a negative regulator of DEPDC1 in TNBC cells and also FOXM1 enhanced stimulating effects of DEPDC1 on tumor growth." (PMID 37689738, 2023). "This invasive form of p-FoxM1 upregulates the expression of IL1A/1B, VEGFA, and IL6 by direct activation, recruiting monocytes and promoting the polarization of M2d-like tumor-associated macrophages (TAMs)." (PMID 37968723, 2023). "The FOXM1 pathway is involved in cell cycle control and DNA damage repair, and it ultimately promotes tumor cell proliferation." (PMID 36424525, 2023). "Current studies have identified FOXM1 as a tumor-specific biomarker with powerful predictive prognostic capacity in HCC." (PMID 37234166, 2023). "In a luminal B experimental PyVmT model, c-Src was shown to stimulate the phosphorylation and activation of FOXM1, and targeting FOXM1 with the FOXM1 inhibitors blocked the cell cycle and tumor initiation, as well as tumor progression." (PMID 37370117, 2023). "The IHC of the same tumor samples likewise revealed robust upregulation of the FOXM1 protein in MPNSTs relative to the benign precursors." (PMID 37686402, 2023). "It has previously been shown that the ATR-CHK1 pathway limits the activity of MMB and FOXM1 to prevent premature expression of mitotic genes during DNA -replication in tumor cells." (PMID 36864753, 2023). "Subgroup evaluations revealed that high FOXM1 expression consistently portended poorer OS across various clinical stratum, including age, gender, pathological stage, and tumor grade." (PMID 37817774, 2023).
tumor (continued). "We suppressed FOXM1 endogenous expression in CAL–27 cells overexpressing DEPDC1 to see if DEPDC1-mediated FOXM1 regulation promotes tumour growth." (PMID 36072787, 2022). "Taken together, these results suggest that PDK1 is involved in FOXM1‐mediated tumour growth in xenograft mice." (PMID 35656815, 2022). "Otherwise, actinin alpha 1 (ACTN1) expression, acyl-CoA dehydrogenase Long-chain (ACADL)/YAP, and YAP/Forkhead Box M1 (FOXM1) are proposed targets for preventing tumor growth and early recurrence of HCC." (PMID 36033517, 2022). "Several studies showed that FOXM1 levels can be altered in tumor cells by protein degradation regulated by ubiquitination and deubiquitination process." (PMID 35241126, 2022). "FOXM1 has a key role in promoting tumor cell proliferation, cell cycle progression, DNA damage repair, angiogenesis, and drug resistance, and elevated FOXM1 correlates with poor prognosis in many cancers." (PMID 35428820, 2022). "FoxM1 intensified HCCA tumor expansion and led to a disappointing prognosis, which is in line with our findings." (PMID 36301031, 2022). "The expression levels of FOXM1 and HuR in tumor xenografts were also decreased after SOCS7 overexpression." (PMID 35624501, 2022). "The FOXM1 is responsible for oncogenic transformation and in tumor initiation, progression, metastasis, and therapy resistance." (PMID 35378133, 2022). "The results showed that depletion of YTHDF1 inhibited tumor proliferation, migration, and invasion, which was partially abolished by overexpression of FOXM1." (PMID 35197112, 2022). "Knockdown of CENPF and FOXM1 synergistically reduced the proliferation of cancer cells and tumor growth in cell-line-derived xenografts." (PMID 35865168, 2022). "The suppression of tumor cell proliferation, migration, and angiogenesis has been observed when downregulating FOXM1." (PMID 35392496, 2022). "Recently, a vital study reported that ALKBH5 elevated in GBM stem cells and maintained tumor initiation through FOXM1 expression and cell proliferation." (PMID 35572524, 2022). "Mechanically, SH3PXD2A-AS1 interacted with DHX9 to enhance FOXM1 expression, promote tumour cell proliferation and accelerate cell cycle progression." (PMID 35410446, 2022). "Then, we extracted the proteins from subcutaneously transplanted tumours and conducted western blotting experiments, which also confirmed reduced FOXM1, STAT3, p-STAT3 and GPX4 expression in subcutaneous tumours from the TST treatment group." (PMID 35859150, 2022). "Conversely, inhibition of FOXM1 function resulted in reduced tumor cell survival and increased apoptosis in vivo and in vitro." (PMID 35053620, 2022). "In order to avoid the bias resulting from non-tumor related death, the relationship of FOXM1 expression with a poor disease-specific survival (DSS) was further evaluated." (PMID 36435510, 2022). "In the nucleus, FOXM1 can trigger the expression of several genes that are involved in tumor initiation processes such as angiogenesis, cell proliferation, cellular migration and invasion." (PMID 36072787, 2022). "PHGDH reportedly modulates FoxM1 expression, thus promoting the expression of the cell proliferation marker gene cyclin D1 and the proliferation of tumor cells." (PMID 35344765, 2022). "After it was confirmed that CDI directly interacts with FoxM1 to exhibit an inhibitory effect, the anti-proliferative effect in the tumor was confirmed." (PMID 35884976, 2022). "FDI-6 is a small-molecule compound that targets FOXM1–DNA interaction and exhibits an anti-tumor effect." (PMID 35680842, 2022). "As a kind of oncogene, FoxM1 is robustly expressed in various human neoplasms and mediates target cytokine expression." (PMID 36301031, 2022). "We also stained the tumor of nude mice transplanted with HepG2 cell line after treatment, and determined that FOXM1-PROTAC can also inhibit the expression of GLUT1 and PD-L1 in vivo, which is consistent with our previous in vitro research results." (PMID 36171633, 2022).
tumor (continued). "In a clinical study, DRP1 expression was associated with FOXM1 and MMP12 expressions in HNC tumor tissues." (PMID 35313071, 2022). "The in vivo results showed that FAM64A depletion significantly reduced tumor size, volume and weight, and that FOXM1 overexpression restored these suppressive effects." (PMID 35538067, 2022). "Relative expression analysis showed that the FOXM1 gene expression rate was considerably different between tumor and normal tissues in a way that FOXM1 was upregulated in tumor tissues P (H) = (0.03)." (PMID 35845311, 2022). "XST-20 was identified to effectively suppress FOXM1 transcriptional activities and exhibit anti-tumor activity." (PMID 35680842, 2022). "In order to fully understand how FOXM1 affects tumor progression and immunity, further mechanistic studies are needed." (PMID 36435510, 2022). "For instance, circ-RNF121 regulates tumor progression along with glucose metabolism via the CRC miR-1224-5p/FOXM1 axis." (PMID 36276867, 2022). "In bladder cancer models, Palbociclib impinges on FOXM1 phosphorylation and activation, exerting its anti-tumor activity independently from Rb-status." (PMID 35712501, 2022). "RCM-1 decreased FOXM1 protein in the tumors, reduced tumor cell growth, and increased tumor cell apoptosis." (PMID 35945194, 2022). "In a mouse xenograft study, engrafted tumor cells with a low expression of FOXM1 led to a reduced tumor size of the xenograft when harvested." (PMID 35887129, 2022). "As a transcriptional factor, FOXM1 plays multiple roles in tumorigenesis and development, such as promoting cell differentiation and proliferation, facilitating tumor metastasis, and invasion." (PMID 36291811, 2022). "Mechanically, POLE2 knockdown promoted the ubiquitination as well as reduced the stability of Forkhead transcription factor (FOXM1), which is a known tumor promotor in GBM, through Aurora kinase A (AURKA)." (PMID 35039475, 2022). "FOXM1 was primarily localized in the nuclei of control tumor cells but exhibited faint immunopositivity in the nuclei of TST‐treated tumor cells." (PMID 35975458, 2022). "Deletion of FOXM1 in HCC inhibited tumor growth, indicating that FOXM1 is required for tumor progression." (PMID 35053606, 2022). "Elevated expression and H3K79me2 methylation of FOXM1 were found also in bone marrow-derived dendritic cells (BMDCs) from tumor-bearing (TBM) and wild-type mice cultured with tumor-conditioned medium." (PMID 35495127, 2022). "In contrast, overexpression of FOXM1 or inhibition of miR-761 restored tumor sphere formation ability." (PMID 35842667, 2022). "We evaluated the expression levels of FOXM1 and PD‐L1 levels on a tumor tissue sample from a patient with LUAD by tissue staining and overall survival analysis." (PMID 35975458, 2022). "In line with bioinformatic analysis, in tumor tissues, significantly higher levels of FOXM1 mRNA and protein were detected." (PMID 36435510, 2022). "Through regulating the JAK2/STAT3/FOXM1 axis, in vivo tumor xenograft assays further demonstrated that knockdown of AGK inhibited tumor development and decreased resistance to paclitaxel." (PMID 36313702, 2022). "In details, we found that the increased FOXM1 protein tumor expression observed in GemNP-treated mice was completely abolished by the concomitant treatment with domatinostat." (PMID 35241126, 2022). "It was found that the expression of FOXM1 in tumor cells was several times higher than that in normal tissue cells." (PMID 36171633, 2022). "FOXM1 stimulates the expression of genes involved in various steps of tumor progression, including epithelial–mesenchymal transition, cell migration, and premetastatic niche formation." (PMID 35955438, 2022). "We also evaluated the effect of HO-ADSC exosomes on MMPs and FOXM1 expression in tumor xenografts using immunohistochemistry." (PMID 36359787, 2022). "Correspondingly, we observed increased ER gene expression in the primary tumor while FOXM1 gene expression was increased in the metastatic sample." (PMID 36318267, 2022).
tumor (continued). "Cyclin D1-positive HCC has been reported to show an aggressive tumor phenotype and a poor prognosis, and it is reasonable to assume that the Wnt/FOXM1 axis promotes an aggressive phenotype of this subset." (PMID 35053606, 2022). "Altogether, these findings indicate that the tumour microenvironment‐induced stabilization of HIF‐1α is involved in the regulation of FOXM1 expression status." (PMID 35656815, 2022). "Other significantly upregulated genes such as SALL4, FOXM1, MYCN, MEP1A and MYBL2 have also been reported to be significantly elevated in HCC and associated with tumor progression." (PMID 36212481, 2022). "It is found that ALKBH5 is closely related to the expression of FOXM1, regulating the level of FOXM1 methylation and tumor progression in many tumors." (PMID 35022030, 2022). "While only the FOXM1, PYROXD1, hTERT and MCTP1 genes were overexpressed in CRC tumor tissues relative to the normal adjacent tissues at all the stages, but FOXM1, PYROXD1, hTERT, PIM3, BMI1, PPARA and MCTP1 were found to have stage-dependent expression." (PMID 35845311, 2022). "An in vivo study validated that SR9009 restrained tumor growth in 22RV1 xenograft models and inhibited FOXM1 and its targeted gene expression." (PMID 36357378, 2022). "They showed that miR-149-5p and miR-149-3p double chains exhibited anti-tumor effects by acting on FOXM1 to inhibit the proliferation, migration, and invasion of renal cancer cells." (PMID 36142734, 2022). "Our analyses of the TCGA HNSCC cohort and multiple GEO datasets revealed a positive correlation between FAM64A and FOXM1, as well as between FAM64A and FOXM1-target genes in HNSCC tumor tissues." (PMID 35538067, 2022). "FoxM1 aggravated tumor development, upregulated FoxP3 expression, increased Treg cells, and reduced CD8+ T cells." (PMID 36301031, 2022). "At mechanistic level, tumor growth impairment was coupled with a decrease in cyclin B1, Rb, Foxm1, Plk1 and phosphorylation of the ribosomal protein S6, a protein phosphorylated by the mTOR pathway and tightly associated with cell cycle progression." (PMID 35712501, 2022). "Tumor tissues were collected, sectioned, and stained to analyze the changes in FOXM1 and PD‐L1 expression levels." (PMID 35975458, 2022). "Continuous daily injections of a cell-penetrating ARF peptides in HCCs in mice with FOXM1 activity has also been shown to inhibit tumor cell proliferation and angiogenesis and significantly increase apoptosis within the HCC region." (PMID 35053606, 2022). "In the gastric cancer cell line SGC7901, TanIIA limits tumor proliferation and migration through suppression of FOXM1, a transcription factor that governs cell fate and promotes tumor progression and metastasis in multiple cancers." (PMID 35432718, 2022). "Xenograft experiments frequently indicated that the consequences of over-expressing DEPDC1 were rescued by suppressing FOXM1 levels, resulting in the reduced progression of tumours." (PMID 36072787, 2022). "Through miR-224-5p/CHSY1 axis, LINC01094 activated by FOXM1 played its tumor-promoting role in the development of CCRCC." (PMID 36727070, 2022). "TRPM2 is a potential therapeutic target to reduce tumor proliferation and increase doxorubicin sensitivity through modulation of FOXM1, E2F1, and cell cycle/DNA repair proteins." (PMID 35428820, 2022). "FOXM1 regulates the expression of several targets involved in tumor growth, angiogenesis, and invasion." (PMID 35680842, 2022). "Taken together, our research demonstrated that circ-FOXM1 worked as a tumor promoter in OS via relieving the inhibition of miR-320a and miR-320b on FOXM1 expression, therefore activating Wnt pathway." (PMID 35799265, 2022). "In the GEPIA database, a positive correlation between DRP1 and FOXM1 in HNC tumor tissues was verified (Fig. [Link], [Link], [Link], [Link], [Link], [Link], [Link])." (PMID 35313071, 2022).
tumor (continued). "Cox regression and Kaplan-Meier analyses revealed that most tumor types had poor prognosis when FOXM1 expression increased, especially KIRP and LUAD." (PMID 36435510, 2022). "We also provided novel insight into a mechanism by which DRP1 mediated tumor growth and motility via FOXM1/MMP12 axis in HNC." (PMID 35313071, 2022). "Taken together, our findings indicated that down-regulated FTO/PHF1 axis triggered the tumor stemness features to drive progression by activating FOXM1." (PMID 35945194, 2022). "FOXM1 is essential for progression to the DNA replication and mitosis stages and stimulates the proliferation of tumour cells during the progression of NSCLC via the Cyclin B1." (PMID 35410446, 2022). "One possible interpretation is that since FOXM1 is a transcription factor, its high level of expression in the initial phases of tumor development can alter cell proliferation and cell-cycle progression, thereby aiding tumor formation." (PMID 35845311, 2022). "The finding in the present study, that the level of FOXM1 mRNA was significantly higher in GBM than in normal brain tissue, suggests that targeting FOXM1 in GBM can suppress tumor progression." (PMID 35978012, 2022). "Consistently, the specific inhibition of FOXM1 using different strategies, such as siRNA, thiostrepton, or peptide inhibitor, has previously been reported to significantly suppress tumour growth in various in vitro and animal models." (PMID 34206484, 2021). "ALKBH5 plays an oncogene that Promotes GSCs proliferation and tumor progression by positively regulating FOXM1 in GBM." (PMID 34521394, 2021). "In fact, FOXO3a behaves as a tumor suppressor, while FOXM1 is a potent oncogene that is widely overexpressed in endocrine-resistant cancers." (PMID 33466512, 2021). "Previous studies have shown that miR‐194 inhibited tumor progression by downregulating FOXM1, RBX1, and KDM5B." (PMID 33605558, 2021). "Gene expression of FOXM1 and its targets BRCA1/2 and RAD51 were investigated together with tumor susceptibility." (PMID 33668819, 2021). "In HGSC patients, shallow whole genome sequencing (sWGS) of circulating tumor DNA (ctDNA) from plasma revealed a 16% increase in chromosome 12p13.33 amplification (location of FOXM1) after the acquisition of chemotherapy resistance." (PMID 34205406, 2021). "Consistently, we found that FOXM1 is differentially expressed in OSCC patient with different tumor stages, genders, races, and molecular subtypes." (PMID 33892811, 2021). "Due to this, FOXM1 serves as a crucial regulator of tumor development, and its overexpression portends a poor prognosis for patients, promoting aggressive tumor phenotype and high resistance to current therapeutic approaches." (PMID 34262016, 2021). "We have discovered four genes of prognostic value (CENPF, FOXM1, MCM4, and TOP2A), and further prioritized MCM4 as a key biomarker of LPS associated with tumor invasiveness (tumor stage, grade, and Ki67 labeling index) and prognostication." (PMID 34178990, 2021). "Studies have shown that FOXM1 is abnormally elevated in a variety of human malignancies and acts as a major activator of tumor cell invasion and metastasis." (PMID 33968297, 2021). "High IGF2, FOXM1 and ETS1 levels also were significantly associated with lymphatic invasion and advanced tumor stage." (PMID 33407516, 2021). "Since FOXM1 is a known regulator of the cell cycle and a downstream molecule of the EGFR/Ras/MAPK signaling pathway, we also analyzed the changes in FOXM1 in the xenograft tumor tissues." (PMID 34830169, 2021). "Referring to FOXM1, it was previously shown to be an important tumor promoter in HCC progression, and its upregulation is correlated with a poor prognosis." (PMID 34830370, 2021). "In the study, we proved that avasimibe retard cell proliferation and tumor growth of CCAs and identified FoxM1/AKR1C1 axis as the potential novel targets of avasimibe." (PMID 34127944, 2021).